CDK5 (cyclin dependent kinase 5)
Diseases named in the same sentence as CDK5 in open-access papers (continued):
Sharing a sentence is not in itself a finding about the gene and the disease.
diabetes (continued). "Inhibition of Cdk5 improves glucose uptake in insulin-resistant neuronal cells via the ERK1/2 pathway, and alleviates cognitive deficits caused by diabetes." (PMID 35966199, 2022). "Intriguingly, here we found that the anti-diabetes drug, metformin, could inhibit Cdk5 activity, and we identified a novel mechanism that metformin inhibited Cdk5 activity by preventing the calpain-dependent cleavage of p35 to p25." (PMID 32670025, 2020). "Then, we showed that the widely used anti-diabetes drug, metformin, could inhibit Cdk5 activity by preventing p35 cleavage into p25." (PMID 32670025, 2020). "Although the existence of p25 was clearly observed in our study, the role of Cdk5/p25 in pathogenesis to diabetes remains unclear; and whether inhibition of Cdk5/p25 activity can protect beta cells from pathology as it does with neurons." (PMID 24039692, 2013). "Cdk5 activity also contributed to the pathogenesis of diabetes mellitus (." (PMID 24039692, 2013). "The present pieces of evidence designate that CDK5 might be a potential drug target for the regulation of glucose-stimulated insulin secretion in the treatment of diabetes mellitus." (PMID 22028710, 2011). "The Cdk5-NGF/Sirt1 axis may be a new target for the treatment of diabetes." (PMID 41181709, 2025). "Therefore, the increased expression level of CDK5 induced by HG may be correlated with podocyte injury in diabetes." (PMID 35874807, 2022). "Recent studies suggest that CDK5 plays crucial roles in physiological functions in glucose-stimulated insulin secretion in pancreatic cells, indicating that CDK5 might be a potential drug target for diabetes mellitus and subsequent DN progression." (PMID 35874807, 2022). "Thus, it is worthwhile to examine whether CDK5 is involved in apoptosis induction in IPCs subjected to continuous accumulation of ER stress through JNK signaling using this Drosophila diabetes model." (PMID 31822470, 2019). "Interestingly, we found that the anti-diabetes drug pioglitazone could inhibit Cdk5 activity by decreasing p35 protein level." (PMID 25875370, 2015). "Furthermore, we revealed that the anti-diabetes drug pioglitazone could suppress Cdk5 hyper-activation in the APP/PS1 mutant mouse hippocampus by decreasing p35 protein level." (PMID 25875370, 2015). "The Cdk5-NGF/Sirt1 axis plays an important role in the damage of islet β cells in diabetes and is a new potential target for the treatment of diabetes." (PMID 41181709, 2025). "Significant correlation (P < .002) existed between decreasing expression of Cdk5 and the decreasing proportion of phosphorylated NFM over the course of diabetes." (PMID 19834568, 2009). "Immunostaining for Cdk5 showed frequent positive staining of small DGR neurons and their nuclei in 2-month diabetic rats, which decreased with duration of diabetes." (PMID 19834568, 2009). "The activation of cyclin-dependent kinase 5 (Cdk5) is involved in the development of diabetes; however, its specific mechanism has not been fully elucidated." (PMID 41181709, 2025). "Recent studies have found that Cdk5 is also closely related to non-neuronal functions such as cancer and diabetes and its complications (Nikhil and Shah, 2023; Liu SY." (PMID 41181709, 2025). "Therefore, our results demonstrate that activation of the novel Cdk5: Cdk5r1 cell cycle kinase may be used as a potential therapeutic entry point for increasing β-cell mass ex vivo for islet transplantation therapy or expansion of endogenous β-cell mass in vivo as a treatment for diabetes." (PMID 26788519, 2016). "With the exception of CDK5 and TCF7L2, no other gene variant showed significant association with any diabetes-related quantitative traits." (PMID 18598350, 2008). "Hence, pharmacologic inhibition of Cdk5 may be ineffective in the obese mice, and MEK and ERK inhibition may provide a better strategy to combat diabetes." (PMID 31910742, 2020).
Insulin resistance (29 papers, 2015 to 2025). Increased resistance towards insulin, that is, diminished effectiveness of insulin in reducing blood glucose levels. "The dysregulation of PPARγ by CDK5 is also implicated in adipose tissue insulin resistance, with CDK5-mediated phosphorylation of PPARγ, a master regulator of adipogenesis, suppressing ADIPOQ expression as observed in our data." (PMID 40975767, 2025). "More recently, post translational modifications, such as PPARγ phosphorylation at Ser273 by CDK5 in adipose tissue, have been linked to insulin resistance trough the dysregulation of expression of a specific subset of genes." (PMID 33329381, 2020). "In 2010, the phosphorylation of PPARγ at Ser245 (in PPARγ1; Ser273 in PPARγ2) by cyclin-dependent kinase 5 (Cdk5) was shown to be linked to insulin resistance." (PMID 31581474, 2019). "Cdk5-mediated phosphorylation of PPARγ at S273 induced by HFD has been linked to insulin resistance." (PMID 30008738, 2018). "Importantly, the current investigation extends these findings to suggest that CDK5 hyperactivation under glucotoxicity may contribute to the loss of beta cell function and insulin resistance, proposing CDK5 inhibitors as potential candidates for the treatment of T2D." (PMID 40224020, 2025). "Our findings demonstrate that MCTs can partially activate PPARγ and inhibit the CDK5-mediated phosphorylation of PPARγser273, thereby ameliorating hyperglycemia and insulin resistance while restoring glucose homeostasis in obese rats." (PMID 38254542, 2024). "Previous research has shown that Cyclin-dependent kinase 5 (CDK5) phosphorylates PPARγ, reducing its function and contributing to insulin resistance." (PMID 37674539, 2023). "Phosphorylation of PPARγ at Ser273 by cyclin-dependent kinase 5 (Cdk5) can affect the expression of distinct PPARγ target genes increasing insulin resistance in mouse models." (PMID 27483259, 2016). "The pharmacological inhibition of MEK and ERK markedly improves insulin resistance in both obese and wild type ob/ob mice, and reversed the effects of the Cdk5 ablation, indicating that the ERK/Cdk5 axis controls the diabetogenic actions of PPARγ." (PMID 27352979, 2016). "Furthermore, compounds that inhibit cdk5‐mediated PPARγ Ser273 phosphorylation have shown promise in reducing insulin resistance." (PMID 40994455, 2025). "It has been found that Cdk5 inhibition by roscovitine could ameliorate insulin resistance and increase glucose uptake in neuronal cells." (PMID 38013469, 2023). "Collectively, this analysis suggests impaired insulin-activation of ERK and CDK5 may contribute to insulin resistance." (PMID 36808134, 2023). "Direct activation of PPAR-γ by ERK has been observed with a concomitant increase in insulin resistance, which could be suppressed by cyclin-dependent kinase 5 (CDK5) in a MEK-dependent manner." (PMID 34069890, 2021). "However, tumor necrosis factor-α (TNF-α), involved in insulin resistance, stimulates CDK5 phosphorylation in an ERK-dependent manner." (PMID 34069890, 2021). "Cdk5 has been shown to induce the phosphorylation of peroxisome proliferator-activated receptor γ (PPARγ) and, subsequently, to stimulate its transcriptional activity, being involved in adipogenesis and insulin resistance." (PMID 33291667, 2020). "Potent synthetic PPARγ ligands such as MRL24 or rosiglitazone (both widely used as insulin-sensitizing anti-diabetic drugs) were proposed to shield Ser273 residue from phosphorylation by Cdk5, thereby restoring expression of adiponectin and overcoming insulin resistance." (PMID 31910742, 2020). "The phosphorylation of PPARγ at Ser273 by Cdk5 decreases the expression of adiponectin through an unknown mechanism, leading to development of insulin resistance." (PMID 31910742, 2020). "Interestingly, adipose tissue specific Cdk5 KO mice have increased PPARγ phosphorylation and insulin resistance due to ERK dependent phosphorylation." (PMID 27483259, 2016).
Insulin resistance (continued). "Recently, it was shown that cyclin-dependent kinase 5 (CDK5)-mediated phosphorylation of PPARγ may be involved in the pathogenesis of insulin resistance and glucose-lowering effects, which provides a new angle to understand the mechanisms of PPARγ activation." (PMID 25827822, 2015). "Two kinases displayed impaired insulin-activation in three or more insulin resistance models, ERK (CI, TNF, AA), and CDK5 (CI, TNF, MPQ, AA)." (PMID 36808134, 2023). "In recent years, it has been found that PPARγ serine 245 (or S273 in PPARγ isoform 2) can be phosphorylated by cyclin-dependent kinase 5 (CDK5), and this posttranslational modification is related with insulin resistance in obese individuals." (PMID 32596392, 2020). "It is important to mention that deletion of CDK5 rather than its inhibition led to insulin resistance due to the activation of ERK which could also phosphorylate S27328." (PMID 34645915, 2021). "Consequently, ablation of Cdk5 did not alleviate insulin resistance." (PMID 31910742, 2020).
neuroblastoma (27 papers, 2006 to 2025). Neuroblastoma (NB) is the most common solid, extracranial childhood tumor. "An in vitro study demonstrated that metformin promotes neurite growth in neuroblastoma cell line by inhibiting Cdk5 in similar manner that of Cdk5 inhibitor roscovitine." (PMID 38842132, 2024). "The modulation of TTCCs by Cdk5 was recently shown, where currents through TTCCs were found to be markedly increased by overexpression of Cdk5 in N1E-115 cells (neuroblastoma cell line), while Cdk5 siRNA knockdown significantly decreased TTCC currents." (PMID 36766802, 2023). "The potential enantioselectivity of MDPV in cytotoxicity and in the expression of neuroplasticity-involved proteins—brain-derived neurotrophic factor (BDNF) and cyclin-dependent kinase 5 (Cdk5)—was also evaluated using SH-SY5Y neuroblastoma cells." (PMID 36903367, 2023). "A probe partner that interacts with CDK5 and a synthetic fluorescent quinolimide-tagged peptide derived from CDK5 calyx were implemented in vitro to detect N2a neuroblastoma and U87 GBM cells." (PMID 37210528, 2023). "Neuroblastoma cells treated with camptothecin had attenuated apoptosis levels when also treated with the Cdk5 inhibitor roscovitine." (PMID 26788519, 2016). "The results presented here confirmed that chick MARCKS is phosphorylated by murine endogenous Cdk5 when it, was overexpressed in neuroblastoma N2a cells, altogether with p35." (PMID 24658276, 2014). "To confirm this interaction, we performed co-immunoprecipitation (co-IP) experiments in the neuroblastoma-glioma NG108-15 cells and found that Cdk5 is associated with the HA-tagged 5-HT6R." (PMID 25078650, 2014). "Further studies indicate a coordinated work between c-Abl and Cdk5 (cyclin-dependent kinase 5) in human neuroblastoma (SHSY5Y) cells." (PMID 23348931, 2013). "Further evidence for direct interaction between GKAP and cdk5 was provided by expressing GFP-tagged GKAP together with HA-tagged cdk5 or myc-tagged p35 in SK-N-MC neuroblastoma cells." (PMID 21829588, 2011). "Recently, we showed tau pathology, neuronal death and reactivation of cell cycle in differentiated neuroblastoma cells overexpressing the CDK5 activator p25." (PMID 18184373, 2008). "To investigate possible consequences of reduced CDK5 activation on Tau pathology, we co-transfected neuroblastoma cells with eGFP-tagged Tau[R406W] mutant along with either WT 5-HT7R or phenylalanine mutants, followed by the analysis of Tau phosphorylation and aggregation." (PMID 38641599, 2024). "In addition, we analyzed co-localization of eYFP-tagged 5-HT7R mutants with CDK5-eCFP after co-expression in neuroblastoma cells." (PMID 38641599, 2024). "To test whether the phenylalanine residues are involved in the interaction of 5-HT7R with CDK5, we performed co-IP experiments in neuroblastoma cells co-expressing mCherry-CDK5 with either HA-tagged 5-HT7R WT or mutants." (PMID 38641599, 2024). "Active CDK5 plays a vital role in some neural functions, and its hyperactivity contributes to various human cancers and some neurodegenerative processes, especially neuroblastoma and GBM." (PMID 37210528, 2023). "Interestingly, oxidative stress induces the upregulation of Cdk5 catalytic subunit p35 in IMR-32 cells, suggesting Cdk5/p35 instead of ERK plays a role in Pin1-mediated Nrf2 nuclear translocation in neuroblastoma cells." (PMID 36829834, 2023). "Our results corresponded to the previous study that metformin may inhibit cell cycle in G0/G1 phase via downregulation of Cdk5 in neuroblastoma." (PMID 30911317, 2019). "To investigate whether T-type (CaV3) channels are substrates of Cdk5, we initially conducted whole-cell patch clamp recordings in the clonal neuroblastoma cell line N1E-115 which express prominent Ca2+ currents through CaV3 channels." (PMID 25760945, 2015).
neuroblastoma (continued). "In this context, the present study reveals a previously unrecognized role for cyclin-dependent kinase 5 (Cdk5) in the regulation of native T-type channels in N1E-115 neuroblastoma cells, as well as recombinant Cav3.1channels heterologously expressed in HEK-293 cells." (PMID 25760945, 2015). "Cdk5 was found to phosphorylate NMHC-B also in the human neuroblastoma SH-SY5Y cell line." (PMID 19534817, 2009). "We also investigated NMHC-B phosphorylation by Cdk5 in human neuroblastoma SH-SY5Y cells." (PMID 19534817, 2009). "Another study showed that two kinases, protein kinase C (PKC) and cyclin-dependent kinase 5 (CDK5), phosphorylate NEIL2 in human SH-SY5Y neuroblastoma cells." (PMID 40761744, 2025). "We demonstrate that NEIL2 is phosphorylated by the two kinases cyclin-dependent kinase 5 (CDK5) and protein kinase C (PKC) in vitro and in human SH-SY5Y neuroblastoma cells." (PMID 36829914, 2023). "Metformin significantly decreased Cdk5 and increased Sox6 during cell differentiation and promoted neuronal differentiation via crosstalk between Cdk5 and SOX6 in neuroblastoma cells." (PMID 36614288, 2023). "In human neuroblastoma (SH-SY5Y) cells, c-Abl targets cyclin-dependent kinase 5 (Cdk5) on tyrosine residue Y15 in response to oxidative stress by hydrogen peroxide." (PMID 22761618, 2012). "AAH and Humbug are over-expressed in SH-Sy5y neuroblastoma cells, and their mRNAs are regulated by insulin/IGF-1 signaling through Erk MAPK, PI3 kinase-Akt, and Cdk-5, which are known mediators of cell migration." (PMID 17156427, 2006). "The present work characterizes IGF-I regulation and downstream signaling pathways through Erk MAPK, PI3 Kinase-Akt, and Cdk-5 that modulate AAH, Humbug, and Junctin expression and directional motility in SH-Sy5y human neuroblastoma cells." (PMID 17156427, 2006). "In addition, we found that resveratrol is able to inhibit Cdk5 activity in mouse neuroblastoma N2a and rat neuroblastoma B104 cell lines (data not shown)." (PMID 21736731, 2011).
amyotrophic lateral sclerosis (26 papers, 2009 to 2025). Amyotrophic lateral sclerosis (ALS) is a neurodegenerative disease characterized by progressive muscular paralysis reflecting degeneration of motor neurons in the primary motor cortex, corticospinal tracts, brainstem and spinal cord. "Hyper-activation of CDK5 has also been implicated in the pathogenesis of Parkinson's disease, amyotrophic lateral sclerosis (ALS) and prion-related encephalopathies." (PMID 31910742, 2020). "Dysfunction of CDK5 has been associated with a number of neurological disorders including Alzheimer’s disease, amyotrophic lateral sclerosis (ALS), and Niemann-Pick type C disease." (PMID 30618612, 2018). "As a result, the dysregulation of CDK5 has been implicated in various diseases, such as Alzheimer’s disease (AD), amyotrophic lateral sclerosis (ALS), Parkinson’s disease (PD) and cancers." (PMID 34895232, 2021). "Previous studies have demonstrated that CDK5 activity is increased in several different neurodegenerative diseases including AD, animal models of amyotrophic lateral sclerosis (ALS) and Niemann Pick type C (NPC) disease." (PMID 36656459, 2023). "Furthermore, marked Cdk5 immunoreactivity was observed in degenerating neurons in the spinal cord of patients with sporadic Amyotrophic lateral sclerosis (ALS) as well as in brain samples from patients with HIV encephalitis, which exhibit more profound cognitive alterations and neurodegeneration." (PMID 36142566, 2022). "The pathological states of neurological disorders and neurodegenerative diseases, including AD, amyotrophic lateral sclerosis, Niemann-Pick type C disease, and ischemic stroke, lead to cleavage of p35 into the more stable p25 by the calcium-dependent protease calpain and to increased CDK5 activity." (PMID 28045138, 2017). "In this case, 4 out of 5 genes from FOSB pathway were mapped to the 2 diseases: CDK5 and GRIA2 to amyotrophic lateral sclerosis and, FOSB and PPP1R1B to drug-induced dyskinesia." (PMID 19194489, 2009).